GIP (gastric inhibitory polypeptide)
Diseases named in the same sentence as GIP in open-access papers (continued):
Sharing a sentence is not in itself a finding about the gene and the disease.
Obesity (continued). "Since acarbose and miglitol were both shown to suppress GIP secretion in response to co-administration of maltose in mice, GIP suppression by α-GIs may contribute, at least in part, to the anti-obesity effect in obese human subjects with diabetes mellitus." (PMID 31509948, 2019). "Although the DIO mouse is useful for analyzing the direct action of HFD on the gut, HFD feeding also induces obesity, which itself may contribute to hypersecretion of GIP." (PMID 31509948, 2019). "In addition, HFD feeding was found to increase mRNA expression of GIP and to induce obesity through the binding of meal-derived free fatty acids to its binding protein, fatty acid binding protein 5 (FABP5)." (PMID 31509948, 2019). "Furthermore, GIP overexpressing mice exhibit reduced diet-induced obesity and improved glucose homeostasis." (PMID 31330984, 2019). "Circulating levels of GIP are increased in obesity in humans and rodents." (PMID 31509948, 2019). "Accordingly, although circulating GIP levels are increased in both DIO and Lepob/ob mice, the underlying mechanisms differ, and the anti-obesity actions of α-GIs and leptin sensitizers may be mediated partly by the suppression of GIP secretion." (PMID 31509948, 2019). "Mice overexpressing GIP show improved glycemic control and resistance to diet-induced obesity." (PMID 29848610, 2018). "Besides its effects to induce insulin secretion upon glucose administration and to regulate fatty acid metabolism, GIP was recently found to be an obesity-promoting factor by acting on adipocytes." (PMID 30158649, 2018). "Furthermore, accumulated evidence suggests that GIP, through its specific receptor, plays an important role in the onset of obesity by promoting energy storage in adipose tissues." (PMID 29494594, 2018). "The genetic ablation of either the GIPR or of GIP-secreting enteroendocrine cells prevented the onset of obesity and increased fat oxidation under high-fat diets through an unknown mechanism." (PMID 27112963, 2017). "Together, these lines of evidence indicate that inhibiting GIP signaling can prevent obesity." (PMID 28970776, 2017). "A series of studies provided evidence supporting the role of GIP in regulating obesity." (PMID 28530680, 2017). "Recently, a relationship between GIP and obesity has been clarified, and it has been understood that GIP has a physiological role in the nutrient uptake into adipose tissues, thereby linking over nutrition to obesity." (PMID 28166771, 2017). "Ten biochemical parameters related to diabetes and obesity were measured by a multiplex kit: c-peptide, ghrelin, glucose-dependent insulinotropic polypeptide (GIP), glucagon-like peptide-1 (GLP-1), glucagon, insulin, leptin, plasminogen activator inhibitor-1 (PAI-1), resistin and visfatin." (PMID 28915840, 2017). "In addition, our previous studies have consistently demonstrated that decreasing the diet-induced GIP response leads to increased energy expenditure and prevents high-fat diet-induced obesity in mice." (PMID 27112963, 2017). "However, native GLP-1 and GIP have a very short half-life because they are rapidly degraded and inactivated by proteolytic enzyme, DPP-4, and GIP is also recognized as an obesity-promoting factor in rats fed a high-fat diet." (PMID 25582643, 2015). "Inhibition of GIP activity by GIP-receptor gene knockout partially prevented diet-induced obesity in mice, suggesting that a decrease in GIP activity may lead to weight loss." (PMID 26266950, 2015). "Conversely, reduced body weight gain has been observed in diet-induced obesity models in a GIPr−/− knock-out mouse, upon immunization with GIP to generate antagonistic antibodies, and upon administration of the GIPr peptide antagonist Pro3GIP or ablation of GIP-producing K cells." (PMID 23689510, 2013). "Interestingly, increasing evidence suggests that GIP and its receptor-mediated effects are a key link between consumption of energy-rich high-fat diets and the development of obesity." (PMID 21935364, 2011).
Obesity (continued). "Subsequent studies with GIPR-/- mice revealed that GIP is an obesity promoting factor." (PMID 20673334, 2010). "GIP has been considered a pro-obesity hormone as a result of its ability to promote lipogenesis." (PMID 20231880, 2010). "Additionally, there are only weak data linking over-nutrition, GIP hypersecretion and obesity in humans." (PMID 20231880, 2010). "Additionally, GIP signaling is required for effective accumulation of nutrients under high-fat diet, and inhibition of GIP signaling not only prevents obesity but also insulin resistance." (PMID 19254363, 2009). "It has been suggested that the gastric inhibitory polypeptide (GIP) may be involved in type 2 diabetes mellitus and obesity." (PMID 19254363, 2009). "Hence, disrupting GIP signaling represents a promising, novel therapeutic strategy for the treatment of obesity." (PMID 18779862, 2008). "Thus, disrupting GIP signaling represents a promising novel therapeutic strategy for the treatment of obesity." (PMID 18779862, 2008). "However, data on the effect of obesity on GIP levels remain limited." (PMID 41575482, 2026). "Other combinations of entero-pancreatic hormones including cagrisema (GLP-1/amylin RA) and the triple agonist retatrutide (GLP-1/GIP/glucagon RA) have also progressed to phase 3 trials as obesity treatments and early data suggests that may lead to even greater WL than tirzepatide." (PMID 38302593, 2025). "Tirzepatide, a dual GIP/GLP-1R agonist, has demonstrated efficacy in reducing body weight and limiting progression to type 2 diabetes in patients with obesity and prediabetes, suggesting that combined GIP/GLP-1 therapy may offer synergistic benefits in obesity-associated IBD." (PMID 40723884, 2025). "However, the opposing idea that endogenous GIP is pro‐adipogenic is supported by findings that mice lacking Gipr are protected against diet‐induced obesity and that humans with loss of function GIPR variants have a lower average body mass index." (PMID 39576749, 2025). "Therefore, the action of GIP may paradoxically affect body weight because the inhibition of endogenous GIP action or the exogenous administration of supraphysiological doses of GIP has anti-obesity effects." (PMID 39940910, 2025). "Furthermore, the inhibition of endogenous GIP or GIPR confers resistance to diet-induced obesity." (PMID 39940910, 2025). "Notably, the GIP/GLP-1 receptor agonist tirzepatide has received FDA approval for T2DM treatment and has demonstrated superior efficacy over semaglutide in promoting weight loss among patients with obesity." (PMID 41149695, 2025). "However, in modern environments with constant food availability, GIP's lipogenic effects in adipose tissue may exacerbate obesity, fueling a cycle of insulin resistance and hyperglycemia." (PMID 39540705, 2025). "By activating GLP-1, GIP, and glucagon receptors, it exerts effects across multiple metabolic pathways, regulating appetite, energy expenditure, and glucose homeostasis, which may provide enhanced efficacy, particularly in patients with obesity and T2DM." (PMID 41211586, 2025). "Consequently, GIP increases the ectopic fat depot in mice, which is a sign of unhealthy obesity." (PMID 39201336, 2024). "Retatrutide – a triple agonist of the glucose-dependent insulinotropic polypeptide (GIP), glucagon-like peptide-1 (GLP-1), and glucagon receptors – at a dose of 12 mg for 48 weeks has been recently associated with a remarkable 24.2% weight loss in adults with obesity." (PMID 39420906, 2024). "We here assessed whether typical pathogens of laboratory mice affect the development of diet-induced obesity and glucose intolerance, and whether colonization affects the efficacy of the GLP-1R agonist liraglutide and of the GLP-1/GIP co-agonist MAR709 to treat obesity and diabetes." (PMID 39019114, 2024). "Furthermore, lipid metabolism and the development of obesity depend on GIP." (PMID 38255264, 2024).
Obesity (continued). "However, subsequent studies have shown that GIP analogs may also have a beneficial effect in the treatment of obesity." (PMID 39408213, 2024). "However, the potential of GLP-1/GIP agonists may represent an unprecedented tool for addressing the complex issue of companion animal obesity." (PMID 38785817, 2024). "Notably, in adults with T2D at high or very high CV risk, AD1 is recommended for the reduction of CV events; if obesity is present, GLP-1 RA or GIP/GLP-1 receptor co-agonists (e.g., tirzepatide) should be considered, independently of HbA1c, for improving weight loss." (PMID 37468901, 2023). "Although GLP-1/GIP co-agonists are one of the most promising drugs to treat obesity and diabetes and have been shown to reduce fasting cholesterol and triglycerides in T2D patients, GIP-dependent contributions to metabolic benefits achieved with this combinatorial therapy remain unclear." (PMID 37592302, 2023). "Further, fasting GIP was neither associated with obesity-related, nor hormone-sensitive cancers." (PMID 36611045, 2023). "GIP infusions resulting in plasma concentrations similar to those observed following oral glucose ingestion, stimulate insulin secretion in a glucose-dependent manner with maximal efficacy at higher postprandial glucose levels, however, its effect is blunted in obesity and T2DM." (PMID 37249754, 2023). "In addition, the effect of the new GLP-1 and GIP dual agonist tirzepatide and the combination drug of orlistat and acarbose would be immensely interesting to investigate in adolescents with obesity." (PMID 38027106, 2023). "Therefore, the lower postprandial GIP concentration induced by the consumption of Jerusalem artichoke might contribute to its anti-obesity effect." (PMID 35440936, 2022). "On the contrary, many studies have even suggested that GIP may promote obesity." (PMID 36313764, 2022). "While the clinical success of these drugs sets the stage for a new era in anti-obesity medication, there remains considerable controversy as to how GIP regulates metabolism and whether GIP receptor agonism or antagonism is a preferred treatment for obesity and T2D." (PMID 35299971, 2022). "Thus, C-peptide, insulin, leptin, PAI, GIP, GLP-1, ghrelin, resistin, and visfatin are closely associated with carbohydrate and lipid metabolism and BMI in obese patients, which contributes to the formation of IR in obesity." (PMID 33959145, 2021). "In addition, the abnormal levels of GLP-1 and GIP lead to abnormal energy metabolism and obesity." (PMID 32596284, 2020). "Furthermore, the active GIP infusion also significantly reduced the injury-induced neointimal hyperplasia and vascular cell proliferation in diabetic db/db mice, an animal model of type 2 diabetes with obesity as well." (PMID 32098413, 2020). "In fact, numerous studies have suggested that GIP may promote obesity." (PMID 32459834, 2020). "Different from GLP-1, GIP has a role in fat accumulation in adipocytes, and, thus, amount of fat consumed may influence directly or indirectly (may through obesity) to glucose tolerance differently, leading to the different nutrient consumption-depending association observed here." (PMID 33009421, 2020). "In addition, our present study suggests that α-GI may be effective in suppressing hypersecretion of GIP in human obesity." (PMID 31509948, 2019). "If this were the case, α-GI might not be effective in ameliorating GIP hypersecretion in patients with excessive fat intake-associated obesity." (PMID 31509948, 2019). "The results of our study also indicate that the meal-induced release in the intestinal anabolic hormone GIP and the gastric hunger hormone ghrelin may be markers of postprandial thermogenesis and therefore may facilitate the design of obesity-preventative meals." (PMID 27112963, 2017). "Consequently, it has been proposed that GIP antagonist treatment, reducing circulating GIP levels with K-cell ablation or vaccination against GIP may be beneficial treatments for obesity." (PMID 22802954, 2012).
Obesity (continued). "In Europeans, who are more prone to obesity induced diabetes, blocking of GIP action on adipocytes may be more beneficial whereas it has been suggested that in Asians, GIP agonists may have a beneficial effect due to greater incidences of diabetes with impaired insulin secretion." (PMID 20673334, 2010). "However, whereas the incretin effect of GIP has been described in detail in humans further investigations will be required to understand the potential role of GIP in linking over-nutrition with obesity in man." (PMID 18779862, 2008). "The use of GLP-1 agonists and, more recently, dual and triple GLP-1/GIP and GLP-1/GIP/glucagon agonists has been proven to be a useful therapy for treating T2DM and obesity." (PMID 41528263, 2026). "Glucagon-like peptide-1 (GLP-1) and dual GLP-1 and glucose-dependent insulinotropic polypeptide (GIP) receptor agonists are highly effective therapies for overweight and obesity due to their potent ability to provide significant amounts of weight loss." (PMID 41897188, 2026). "Tirzepatide, a dual glucagon-like peptide-1 (GLP-1)/glucose-dependent insulinotropic polypeptide (GIP) receptor agonist, is increasingly prescribed for obesity and glycemic control." (PMID 42109981, 2026). "Semaglutide, a glucagon-like peptide-1 receptor agonist (GLP-1), and tirzepatide, a dual glucose-dependent insulinotropic polypeptide and GLP-1 receptor agonist (GIP/GLP-1), are among the leading pharmacological options for obesity treatment." (PMID 41664890, 2026). "Evidence supporting the use of GLP‐1 RAs and dual GIP/GLP‐1 RA is more consistent in patients with HFpEF and obesity." (PMID 41309245, 2025). "We describe secretion patterns, receptor distributions, and distinct actions of GIP and GLP-1, as well as alterations in incretin signaling in T2DM and obesity." (PMID 41515907, 2025). "Trials investigating newer potential anti-obesity medications, including co-agonists and tri-agonists that target peptides such as GLP-1, glucose-dependent insulinotropic polypeptide (GIP), amylin, and glucagon are underway." (PMID 41153573, 2025). "Novel pharmacotherapies developed to target obesity include glucagon-like peptide-1 (GLP-1) receptor agonists and glucose-dependent insulinotropic polypeptide (GIP) receptor agonists." (PMID 40727552, 2025). "There was an upsurge of GIP focused research since the extended-release GLP-1R and GIPR co-agonist tirzepatide became available for T2D and obesity treatment." (PMID 40687579, 2025). "Tirzepatide, a dual GIP/GLP-1 receptor agonist, is approved for obesity and type 2 diabetes in adults." (PMID 41153573, 2025). "The introduction of GLP-1 RAs and GIP/GLP-1 RAs was met with immediate enthusiasm, heralding a transformative era in the treatment of obesity." (PMID 40507553, 2025). "Tirzepatide is the only licenced GLP-1/GIP co-agonist for obesity, with several more GLP-1/GIP co-agonists in development." (PMID 40741227, 2025). "Retatrutide (LY3437943) is the first GLP-1/GIP/GCG triple agonist to complete phase 2 trials, with phase 3 studies ongoing for obesity and/or T2D management." (PMID 40741227, 2025). "Concerning the role of TRZ in reducing the deleterious effects of obesity on the pathogenesis of AD, it has been demonstrated that TRZ can alleviate brain GIP signaling." (PMID 40498212, 2025). "Tirzepatide (TZP), a dual GIP/GLP-1 receptor agonist, improves glycemic control and reduces body weight and the liver fat content in patients with obesity and T2D." (PMID 40805994, 2025). "A study from endocrinologists and PCPs highlighted cost as a barrier to appropriate therapy for obesity, with PCPs more familiar with GLP-1 RAs than glucagon or GIP RAs." (PMID 40718234, 2025). "GIP levels are reportedly high in obese patients and in mice with high fat diet (HFD)-induced obesity." (PMID 39940910, 2025).
Obesity (continued). "Positive clinical results from tirzepatide (originally named LY3298176), a long-acting “sequence-mixed” GIP and GLP-1 receptor agonist, led to FDA approval for T2DM and obesity treatment." (PMID 40532005, 2025). "Incretin-based therapies have revolutionized the management of type 2 diabetes and obesity by harnessing the physiological actions of gut-derived hormones such as glucagon-like peptide-1 (GLP-1) and glucose-dependent insulinotropic polypeptide (GIP)." (PMID 41155633, 2025). "A new generation of anti-obesity medications (AOM), the Glucagon-like peptide-1 (GLP-1) / Gastric inhibitory polypeptide (GIP) / Glucagon receptor agonists, lead to 15–20% weight loss and are transforming the clinical care of people with obesity." (PMID 39149290, 2025). "Recently, the SUMMIT trial assessed the dual GIP/GLP‐1 RA tirzepatide (subcutaneous, once‐weekly, up to 15 mg) in 731 patients with obesity‐related HFpEF (LVEF ≥50%; median BMI 38 kg/m2)." (PMID 41309245, 2025). "Meanwhile, tirzepatide, a dual glucose-dependent insulinotropic polypeptide (GIP) and glucagon-like peptide-1 (GLP-1) receptor agonist, is an emerging therapeutic option for type 2 diabetes and obesity." (PMID 40911613, 2025). "Recently, the 3-year safety outcomes of the SURMOUNT-1 trial with tirzepatide (dual GIP/GLP-1 RA) were reported, confirming its efficacy in reducing weight and delaying progression to T2D in persons with both obesity and prediabetes." (PMID 40316962, 2025). "Tirzepatide (TRZ) is a dual agonist of glucagon-like peptide 1 (GLP-1) and gastric inhibitory polypeptide (GIP) receptors that were recently approved for the treatment of type 2 diabetes (T2D) and obesity." (PMID 40498212, 2025). "Tirzepatide, a dual GIP and GLP-1 receptor agonist, is increasingly used for type 2 diabetes and obesity." (PMID 40911613, 2025). "Tirzepatide, a dual glucose-dependent insulinotropic polypeptide (GIP) and glucagon-like peptide-1 (GLP-1) receptor agonist, is increasingly prescribed for the treatment of type 2 diabetes and obesity." (PMID 41425685, 2025). "The drug Tirzepatide is a dual glucose-dependent insulinotropic polypeptide (GIP) and glucagon-like peptide-1 receptor (GLP1-R) agonist used for the treatment of T2DM and obesity." (PMID 41155431, 2025). "Tirzepatide (LY3298176) is a first-in-class dual GIP and GLP-1 receptor agonist approved for type 2 diabetes and obesity." (PMID 41439084, 2025). "Recent pharmacologic advancements, particularly with incretin-based therapies such as tirzepatide, a dual GIP and GLP-1 receptor agonist, have redefined the landscape of obesity management." (PMID 41393538, 2025). "Studies suggest that dual GIP/GLP-1 receptor agonists provide beneficial metabolic effects in individuals with type 2 diabetes and obesity." (PMID 40806228, 2025). "Currently the FDA has approved 3 GLP-1 RA s for the treatment of obesity: liraglutide, semaglutide, and tirzepatide (the latter is a GLP-1/glucose-dependent insulinotropic polypeptide [GIP] dual agonist)." (PMID 40522819, 2025). "Given the widespread clinical application and proven effectiveness of GLP-1 RAs, GLP/GIP RA for managing T2DM and obesity, clinicians should remain aware of potential gastrointestinal side effects." (PMID 40941750, 2025). "Data from a retrospective registry study investigated the efficacy and safety of the dual GIP‐GLP‐1RA Tirzepatide as adjunctive treatment in T1D patients with overweight or obesity, most having class III obesity (mean BMI of 41.2%)." (PMID 40914967, 2025). "The development of triple agonists for obesity has built upon successes of several dual combinations of entero-pancreatic hormone receptor agonists, in particular, GLP-1/GIP dual agonists and GLP-1/GCG dual agonists." (PMID 40741227, 2025).